HLA-DRB1 (major histocompatibility complex, class II, DR beta 1)
Diseases named in the same sentence as HLA-DRB1 in open-access papers (continued):
Sharing a sentence is not in itself a finding about the gene and the disease.
COVID-19 (continued). "HLA-A*02 (n=24, 40%), HLA-A*01 (n=7, 11.7%), HLA-B*50 (n=6, 10%), HLA-B*35 and HLA-B*38 (n=5, 8.3%), HLA-DRB1*07 (n=12, 20%), and HLA- DRB1*04 (n=9, 15%) were most identified in all COVID-19 patients (n=30)." (PMID 36110850, 2022). "We report a 45-year-old Japanese male with positive for HLA-DR4/HLA-DRB1*0405, who developed bilateral panuveitis resembling Vogt-Koyanagi-Harada (VKH) disease after the second dose of Pfizer-BioNTech COVID-19 mRNA (BNT162b2) vaccine." (PMID 36248859, 2022). "Furthermore, the frequency of HLA-DRB1*04:01 was higher in asymptomatic individuals, suggesting its association with resistance; and the frequency of the haplotype DQA1*01:01-DQB1*05:01-DRB1*01:01 was lower in the asymptomatic group, suggesting its correlation to COVID-19 severity." (PMID 36202985, 2022). "Our DEG analysis showed increased levels of HLA-DRA, HLA-DRB1 and HLA-DRB5 in CD16+ monocytes from mild COVID-19 cases compared to healthy donors." (PMID 34108966, 2021). "Patients with COVID-19 showed downregulation of genes involved in the AP-1 transcription factor pathway (including JUN, JUNB, JUND, and FOSB) as well as HLA genes (including HLA-E, HLA-DRB1, HLA-DRA, and HLA-DPB1)." (PMID 36992700, 2023). "They found that HLA-DRB1*04:01 is significantly more frequent in severe COVID-19 patients compared to the asymptomatic staff group; they found thatHLA-DQA1*01:01, HLA-DQB1*05:01, and HLA-DRB1*01:01 are less frequent in the asymptomatic group compared to the background population." (PMID 37192180, 2023). "However, in severe COVID-19 cases HLA-DRA and HLA-DRB1 expression was decreased, while HLA-DRB5 remained unaltered compared to healthy controls." (PMID 34108966, 2021). "Further, we investigated the expression of MHC class II molecules (MHCII) and Fc receptors (FcRs) and found that they were broadly upregulated in APCs in lungs of mild COVID-19 patients, with a MHCII subset (HLA-DRA, HLA-DMB, HLA-DRB1, HLA-DPB1, HLA-DQB1, HLA-DMA) were downregulated." (PMID 34502134, 2021). "In contrast, genes involved in antigen presentation through MHC II presented a “valley” pattern, with under-expression among TUBE early compared to HLTY and COVID-19 compared to INFL, which strikingly predominated in TUBE early (e.g. HLA-DRA, HLA-DRB1, HLA-DQA1, CD74/Ii/CLIP/SLIP)." (PMID 34135895, 2021). "Regarding the downregulated geneset, MHC II molecules, including HLA-DQA1, HLD-DRA, HLA-DRB1, HLA-DMB, HLA-DMA, etc., and cytokine/chemokine genes, including IL1B, TNF, CCL3, CCL4, and CXCL8 were expressed at lower levels in COVID-19 patients, especially those with severe diseases." (PMID 33101705, 2020). "Previous studies have suggested that HLA-DRB1*11 may provide protection against severe forms of COVID-19 and since the present study mainly included non-severe cases, it is possible that the prevalence of HLA-DRB1*11 was higher in this population." (PMID 37845715, 2023). "The allele frequencies of HLA-DRB1*15 were 17.6% and 22.2% in patients with non-vaccine-related disease onset before and during the COVID-19 era, respectively, while no case of HLA-DRB1*15 was identified among patients with a new diagnosis of MS post-COVID-19 vaccine." (PMID 38674141, 2024). "Interestingly, MSCs from patients with mild COVID-19 transcribed high levels of CD86, HLD-DRA, HLA-DRB1, and HLA-DRB5, suggesting that these cells may play a role in the priming of T lymphocytes and act directly and indirectly in the orchestration of the immune response facing the disease." (PMID 35095855, 2021).
sarcoidosis (53 papers, 2009 to 2025). Sarcoidosis is a multisystemic disorder of unknown cause characterized by the formation of immune granulomas in involved organs. "For example, HLA-DRB1*0301 is associated with the abrupt onset of sarcoidosis and a rapid, spontaneous resolution of the disease." (PMID 39904950, 2025). "HLA-DRB1 is a key gene linked to various subphenotypes in sarcoidosis, including target-organ involvement and disease persistence." (PMID 41026325, 2025). "In some cases, the allele status is similar between sarcoidosis and lymphoma: the HLA-DRB1*07 is associated with an increased risk for sarcoidosis and Hodgkin’s lymphoma." (PMID 39859309, 2025). "Studies have demonstrated that certain human leukocyte antigen (HLA) haplotypes, particularly HLA-DRB1 1101, are linked to an increased risk of developing sarcoidosis." (PMID 40821295, 2025). "Genome-wide association studies (GWAS) in sarcoidosis have identified multiple susceptibility loci, particularly within the HLA class II region including HLA-DRB1, DQA1, and DQB1, implicating antigen presentation to CD4+T cells in pathogenesis." (PMID 41197661, 2025). "Regarding clinical phenotypes of sarcoidosis, HLA-A*01:01, HLA-B*08:01, HLA-C*07:01, HLA-DRB1*03:01, HLA-DQA1*05:01, and HLA-DQB1*02:01 associated with Löfgren’s syndrome." (PMID 37153085, 2023). "Our observations, therefore, extend findings from previous reports from sarcoidosis association studies across populations that showed the link between HLA-DRB1*03:01 and sarcoidosis patients, especially in the group with a better prognosis." (PMID 37153085, 2023). "NOTCH4 was identified as a sarcoidosis-associated risk and severity gene in AA populations, and HLA-DRB1 SNPs as risk/severity SNPs for progressive sarcoidosis in European descent subjects and disease susceptibility in African descent subjects." (PMID 38390497, 2023). "Regarding systemic disease, previous reports from Swedish, UK, and Turkish populations associated alleles of the HLA-DRB1 locus (HLA- DRB1*04 -DRB1*15) with extrapulmonary sarcoidosis." (PMID 37153085, 2023). "In our study, HLA-DRB1*15:01 and HLA-B*07:02 were also observed as risk factors for sarcoidosis at the primary significance level." (PMID 37153085, 2023). "We report two variants, HLA-DQB1*06:02, and HLA-DQB1*06:04, as risk factors for sarcoidosis, and three variants, HLA-DRB1*01:01, HLA-DQA1*03:01, and HLA-DQB1*03:02 as protective factors." (PMID 37153085, 2023). "HLA-DRB1 is the HLA locus most often mentioned in connection with sarcoidosis; 41 different variants in this locus were determined by HLA genotyping in our patient group." (PMID 35661780, 2022). "Mirfeizi and coworkers described that patients with sarcoidosis from Northeast Iran have an increased HLA-DRB1*07 allele frequency compared with healthy controls." (PMID 36359012, 2022). "The ACCESS project (A Case Control Etiologic Study of Sarcoidosis) was the first to show that HLA-DRB1 (*1101) and HLA-DPB1 (*0101) alleles contributed significantly to the risk of sarcoidosis, in both black and white populations." (PMID 32823753, 2020). "Certain MHCII molecules, primarily HLA-DPB1 in CBD and several HLA-DRB1 alleles in sarcoidosis, increase disease susceptibility." (PMID 32256501, 2020). "The major genetic factor for sarcoidosis is the HLA-DRB1*0301 allele that is located in the major histocompatibility complex (MHC) class II region." (PMID 31819081, 2019). "Together, these studies reveal the presence of linked in situ recognition of vimentin by both T- and B-cells in HLA-DRB1*03+ sarcoidosis patients, associated with a selective humoral immune response to the vimentin C-terminus." (PMID 30038611, 2018). "In summary, our results demonstrate sarcoidosis to be associated with an antigen- and HLA-DRB1*03-restricted humoral immune response to vimentin." (PMID 30038611, 2018).
sarcoidosis (continued). "Genetic susceptibility to sarcoidosis has been found to be independently related to both HLA Class I and HLA Class II groups such as HLA-DRB1, HLA-DR5." (PMID 28253271, 2017). "HLA-DRB1*03 has been associated with sarcoidosis with favorable prognosis and Löfgren’s syndrome in several populations with European descent, especially in Scandinavian countries." (PMID 28469621, 2017). "Previous sarcoidosis candidate gene studies focused on granuloma formation and immune response pathways implicated several genes linked to sarcoidosis susceptibility including HLA antigens such as class I HLA-B8 and HLA-DRB1." (PMID 22984568, 2012). "Polymorphisms within butyrophilin-like 2 (BTNL2) gene - located in close proximity of the HLA complex on chromosome 6 - have been associated with sarcoidosis independently of HLA-DRB1 alleles." (PMID 23075428, 2012). "Odds ratios (OR) of HLA-DRB1 alleles in all patients with sarcoidosis as compared to healthy Swedish controls (n = 1366)." (PMID 20187937, 2010). "Intriguingly, sarcoidosis has even been suggested to be an “autoimmune disorder” considering the evidence of in situ recognition of vimentin by both T- and B-cells in HLA-DRB1*03+ sarcoidosis patients, associated with the detection of anti-vimentin antibodies in BALF." (PMID 39062076, 2024). "At the same time, the HLA-DRB1*04/*15 genes are associated with the risk of developing extrapulmonary manifestations of sarcoidosis, such as lesions of the skin, superficial lymph nodes, eyes, nervous system, kidneys, parotid and salivary glands, heart, liver, spleen, and bone marrow." (PMID 39598118, 2024). "HLA-DRB1*1101 is reported as risk factor for sarcoidosis in both blacks and whites." (PMID 37161980, 2023). "Additionally, HLA-DRB1 * 03:01 was associated with an acute form of sarcoidosis called Lofgren’s syndrome, whereas HLA-DRB1 * 1101 was associated with chronic sarcoidosis." (PMID 37110254, 2023). "We determined variant HLA-DRB1*11:01 as a risk factor for more advanced CXR stages of sarcoidosis." (PMID 37153085, 2023). "The association with male sex and HLA-DRB1*07 may indicate an influence from sex hormones and a certain genotype on the sarcoidosis lymphopenia phenotype." (PMID 37161980, 2023). "Another study showed HLA-B and HLA-DRB1 association with both sarcoidosis and thyroid disease." (PMID 37399514, 2023). "In conclusion, while the HLA region has long been consistently associated with sarcoidosis, the majority of the reports focused on populations of Northern/Western Europe origin and pointed to class II loci, namely the HLA-DRB1, in line with its major role in antigen presentation." (PMID 37153085, 2023). "HLA-DRB1 * 1101 has been associated with susceptibility to sarcoidosis." (PMID 37110254, 2023). "Second, we determined HLA-DRB1*14:54 as a risk factor for sarcoidosis in Koreans." (PMID 35661780, 2022). "Moreover, HLA-DRB1 alleles are linked to more severe forms of sarcoidosis, including a higher burden of lung granulomas as well as extrapulmonary manifestations such as hypercalcemia and ocular disease." (PMID 35717175, 2022). "In patients with sarcoidosis, HLA-DRB1*04 is associated with eye involvement." (PMID 33912164, 2021). "In the United States, HLA-DRB1*11:01 and HLA-DRB1*15:01 are both associated with sarcoidosis." (PMID 32256501, 2020). "Of the HLA alleles, only HLA-DRB1*0803 showed genome-wide significance as a risk factor for sarcoidosis (PGC = 4.1 × 10−8, OR = 1.82, 95% CI = 1.46–2.26); HLA-DQB1*0601 showed the next highest significance as a risk allele for sarcoidosis (PGC = 1.5 × 10−7, OR = 1.32, 95% CI = 1.12–1.56)." (PMID 32826979, 2020). "In addition, several studies have found a connection between HLA class II molecules and immune-mediated disorders, such as susceptibility loci in HLA-DRB1 for sarcoidosis and pemphigus and susceptibility loci in HLA-DQA1 for achalasia and celiac diseases." (PMID 31827636, 2019).
sarcoidosis (continued). "Heterogeneity of these HLA effects in sarcoidosis across ancestries was observed in the ACCESS study suggesting that while the HLA-DRB1*1101 allele was associated with sarcoidosis in AAs and EAs, the HLA-DRB1*1501 allele was associated with sarcoidosis only in EAs." (PMID 22952805, 2012). "In conclusion, this study reveals the importance of sub-grouping sarcoidosis patients when calculating genetic risk factors, since we here found several distinct differences between the patient subgroups and describes new associations between specific HLA-DRB1 alleles and sarcoidosis." (PMID 20187937, 2010). "Also HLA-DRB1*1501 (strongly linked to DQB1*0602) has previously been associated with a chronic course of sarcoidosis and severe pulmonary sarcoidosis." (PMID 20187937, 2010). "Also, the HLA alleles associated with sarcoidosis may increase the risk of tuberculosis, e.g., HLA-DRB1*04, or decrease it, e.g., HLA-DRB1*03." (PMID 40724571, 2025). "Similarly, it has been found that HLA-DRB1*1101 could be considered as a risk factor for development of sarcoidosis, again suggesting the hypothetical connection role of genetics." (PMID 37219757, 2023). "In contrast, HLA-DRB1*03, HLA-DRB1*11, HLA-DRB1*12, HLA-DRB1*14, and HLA-DRB1*15 are linked to an increased susceptibility to sarcoidosis." (PMID 39904950, 2025). "For instance, the HLA-DRB1*03, DRB1*07, and DRB1*15 genotypes are predisposing risk factors for the development of sarcoidosis." (PMID 40141400, 2025). "To conclude, findings from this study indicate that severe SAHC in Swedish sarcoidosis patients is associated with sun exposure, elevated s-ACE and HLA-DRB1*04." (PMID 39939699, 2025). "Patients with sarcoidosis, presenting as Löfgren’s syndrome (LS), have demonstrated stimulation of CD4+ T cells by the A. nidulans antigen, albeit dependent on the HLA-DRB1*03 allele." (PMID 40724571, 2025). "As an example, the combination of HLA-DRB1*01 and TNFA2 predisposes Europeans to favorable prognosis, but is associated with poor prognosis and cardiac manifestation of sarcoidosis in a Japanese cohort." (PMID 37621457, 2023). "This study was designed to assess the association of HLA-DRB1 alleles, clinical characteristics and BALF cells with PB lymphopenia, in patients with sarcoidosis." (PMID 37161980, 2023). "HLA-DRB1*11:01 frequency was four times higher in CXR stages 2−4 than in CXR stage 1 and this variant was associated with higher sarcoidosis CXR stages (pcorr = 0.001) also when comparing carriage rates." (PMID 37153085, 2023). "Recently HLA-DRB1*03:01 and HLA-DQA1*05:01 alleles were associated with better prognosis in sarcoidosis, although MHC-related studies differ significantly among specific populations." (PMID 38390497, 2023). "The linkage of variants HLA-B*08, HLA-DRB1*03:01, and HLA-DQB1*02:01 with good prognosis of sarcoidosis was observed previously in a Croatian population." (PMID 37153085, 2023). "In this context, we think that our finding of an association with PB lymphopenia and HLA-DRB1*07 is interesting as genetic polymorphism of the TNF-α gene has been connected to HLA-DRB1 variants and response to TNF-α inhibitor treatment in sarcoidosis." (PMID 37161980, 2023). "Variants HLA-DRB1*04:06, HLA-DRB1*13:02, HLA-DRB1*14:01 were protective and variant HLA-DRB1*14:03 acted as a risk allele for sarcoidosis, associations being significant on a primary level." (PMID 35661780, 2022). "Variants previously associated with sarcoidosis risk (HLA-C*03:04, HLA-DRB1*12:01, HLA-DRB1*14:54) and a known protective variant HLA-DPB1*04:01, were associated with sarcoidosis in Koreans." (PMID 35661780, 2022). "After correction for multiple comparisons, alleles HLA-DRB1*14:54 (pcorr = 2.31 × 10−05) and HLA-DRB1*12:01 (pcorr = 9.12 × 10−05) were identified as risk factors for sarcoidosis." (PMID 35661780, 2022).
sarcoidosis (continued). "Among the HLA genes, multiple allele forms of HLA-DRB1 (HLA-DRB1*03, 11, 12, 14, and 15), which is an MHC class II molecule, and BTNL2 have been associated with sarcoidosis." (PMID 33912164, 2021). "The analysis of this particular T-cell subset add value especially in sarcoidosis cohorts where Löfgren’s syndrome is frequently occurring and/or where HLA-DRB1*03 is common e.g. in Scandinavian countries." (PMID 32111204, 2020). "They share the same IL23R variant (rs117633859), and they are both associated with class II HLA polymorphisms (sarcoidosis: HLA-DRB1*03, *08, *09, *11, *12, *14, and *15; VKH disease: HLA-DRB1*04) as risk factors." (PMID 32826979, 2020). "Similar to most immune-mediated diseases, disease susceptibility in CBD and sarcoidosis is driven by the expression of certain MHCII molecules, primarily HLA-DPB1 in CBD and several HLA-DRB1 alleles in sarcoidosis." (PMID 32256501, 2020). "Henceforth, the functional role of the HLA-DRB1 and smoking in sarcoidosis shall be further explored." (PMID 31819081, 2019). "Bronchoalveolar lavage fluid (BALF) and serum from 48 sarcoidosis patients and 15 healthy volunteers were typed for HLA-DRB1*03 and titrated for antibodies to full-length vimentin, vimentin truncations, and total IgG and IgA by ELISA." (PMID 30038611, 2018). "Together, these data suggest a self-contained in situ adaptive immune response to the vimentin C-terminus in sarcoidosis patients, which is particularly pronounced in those expressing HLA-DRB1*03." (PMID 30038611, 2018). "These two observations alone suggest a coordinated epitope shift to the vimentin C-terminus for both B- and T-cell in situ adaptive immunity especially in HLA-DRB1*03+ sarcoidosis patients." (PMID 30038611, 2018). "We hereby demonstrate that there is indeed a strong enrichment of BALF C-terminal AVAs in HLA-DRB1*03+ sarcoidosis patients." (PMID 30038611, 2018). "Due to linkage disequilibrium between HLA groups, it is sometimes hard to determine which is the involved genetic predisposing factor, as in the case of HLA-DRB1 and HLA-DQB1, as both were correlate to sarcoidosis, and to one another." (PMID 28253271, 2017). "One group identified a number of vimentin peptides by mass spectrometric sequencing after affinity-purification of HLA-DR molecules (HLA-DRB1*0301) from bronchoalveolar lavage (BAL) cells of sarcoidosis patients." (PMID 28114394, 2017). "In highly specialized referral centres for sarcoidosis, patients presenting with Löfgren’s syndrome are routinely genotyped for the HLA-DRB1*0301/DQB1*0201 (DR3) haplotype." (PMID 23075428, 2012). "Subsequently, HLA Class II antigens - encoded by HLA-DRB1 and DQB1 alleles - have been consistently associated with sarcoidosis." (PMID 23075428, 2012). "We replicated associations for several previously reported sarcoidosis susceptibility risk loci in our AA collection including MHC Class II region genes (HLA-DRA, HLA-DRB5, HLA-DRB1, and HLA-DQA1), BTNL2, RAB23, and ANXA11." (PMID 22952805, 2012). "Sarcoidosis-associated HLA class II alleles, including HLA-DRB1*03:01 and HLA-DRB1*15:01, may limit the presentation of C. acnes antigens, favoring Th1/Th17 polarization." (PMID 40837573, 2025). "Several HLA alleles have been identified with disease phenotypes in sarcoidosis.HLA-DRB1*01 and HLA-DRB1*04 exhibit a negative correlation with sarcoidosis, suggesting they confer a protective role against the disease." (PMID 39904950, 2025). "This residue is found in the three haplotypes most associated with sarcoidosis (HLA‐DRB1*1101, HLA‐DRB1*1201, and HLA‐DRB1*1501) and might have a fundamental role in peptide binding and affect T‐cell recognition." (PMID 32368866, 2020). "Interestingly, HLA-DRB1*03 carriage is frequent in both systemic lupus erythematosus (more than 60%) and sarcoidosis (30–40% of all patients; ~70% of LS patients)." (PMID 30038611, 2018).